NOTCH1 (notch receptor 1)
Diseases named in the same sentence as NOTCH1 in open-access papers (continued):
Sharing a sentence is not in itself a finding about the gene and the disease.
tumor (continued). "Much of the data linking NOTCH1 with outcomes in ACC stems from clinical investigations, which either evaluate its prognostic significance or explore tumor responses to NOTCH1 inhibitors." (PMID 40789681, 2025). "In contrast, forskolin has been reported to promote VM formation in choriocarcinoma by activating the Notch-1 signaling pathway via cAMP, representing the only known case in which single natural product facilitates tumor VM formation." (PMID 41019994, 2025). "NOTCH1 p.T311P (eliminates O-fucose site on EGF8) and p.T349P (eliminates O-fucose site on EGF9) missense mutations were found in patients’ tumor samples by whole-exome sequencing." (PMID 40286076, 2025). "We found that protein expression was upregulated in 43.57%, 45%, 56.31%, and 42.71% of tumor tissue in Notch1, Notch2, Notch3, and Notch4, respectively." (PMID 41027955, 2025). "NOTCH1 mRNA expression was found to be normally distributed across the tumour tissues of the present cohort." (PMID 39153127, 2025). "In contrast to the tumour suppressor NOTCH1, NOTCH2 and NOTCH3 have demonstrated an oncogenic role in BCa and correlation with poor prognosis." (PMID 41008920, 2025). "The relative NOTCH1 mRNA expression was determined in 414 tumour samples, using quantitative PCR in a prospective, multicenter cohort (Prognostic Assessment in Routine Application (PiA), 2009–2011, NCT01592825) of 1,270 female eBC patients." (PMID 39153127, 2025). "In this work, we discover NOTCH1 as a potential predictive biomarker for ICB and show that NOTCH1 can drive both antigen presentation and tumor T cell infiltration in SCLC by reexpression of STING." (PMID 40627448, 2025). "The FGF/FGFR1/NOTCH1 within RB1 variant group has a dramatically inflamed microenvironment, showing higher inner‐tumor CD8+ T cell infiltration." (PMID 40001320, 2025). "Given the established roles of Notch1 in NSCLC proliferation, migration, and tumor immunity, along with its capacity to induce Akt phosphorylation (p-Akt), we investigated the involvement of the Notch1/Akt pathway in CRTC1-mediated regulation." (PMID 40977688, 2025). "Western blot analysis confirmed that SAC suppressed YTHDF1 and downstream NOTCH1 expression in tumor tissues." (PMID 41423446, 2025). "Conversely, in cutaneous squamous cell carcinoma, Notch1 functions as a tumor suppressor, preserving epidermal stem cell homeostasis and promoting terminal differentiation." (PMID 41373772, 2025). "The results showed that in both paired and unpaired samples, the expression of NOTCH1 in tumor tissues was significantly higher than that in normal cervical tissues (all p<0.05)." (PMID 41306984, 2025). "Some reports suggest that Notch1 is highly expressed in GBMs, implying a potential role as a tumour promoter." (PMID 40100070, 2025). "When tumor cells activate NOTCH1, they prevent apoptosis and continue growing in a malignant manner." (PMID 40672020, 2025). "In this study, we revealed that CRTC1 knockdown amplifies anti-PD-L1 tumor immunity via the Notch1/Akt pathway, improving atezolizumab efficacy and response rates." (PMID 40977688, 2025).
tumor (continued). "Loss or inhibition of YTHDF1 disrupted NOTCH1 translation, induced DNA damage, and thus synergized with commonly used chemotherapies in CRC, 5-FU and Oxaliplatin, to potentiate tumor eradication in vivo." (PMID 41423446, 2025). "Luteolin treatment disrupts this axis by releasing miR‐130a‐3p, which suppresses Notch1 signaling and thereby inhibits tumor growth and angiogenesis." (PMID 40796179, 2025). "For example, circRNA CDR1as (Cerebellar Degeneration-Related Protein 1-antisense RNA) acts as a sponge for miR-7, relieving miR-7’s inhibitory effect on Notch1, thereby activating Notch signaling and promoting tumor cell proliferation and migration." (PMID 40621472, 2025). "In contrast, in cutaneous squamous cell carcinoma (cSCC), Notch1 exhibits a tumor-suppressive role, inhibiting tumor initiation by maintaining epidermal stem cell homeostasis and promoting terminal differentiation." (PMID 41050674, 2025). "Our data demonstrated an interplay between the tumour suppressor activity of Bcor and Notch1 in RT pathogenesis with potential for tumour targeting." (PMID 40113912, 2025). "An overexpression of NOTCH1 in the tumour microenvironment inactivates Bcl-2-associated X protein (BAX) and Bcl-2-associated Death promoter (BAD) proteins, which help tumour cells survive and prevent immune cells from killing them." (PMID 40672020, 2025). "Tumours in the Notch‐1 activation group exhibited significantly greater size and weight compared to the other groups, indicating that Notch‐1 activation promoted orthotopic tumour growth in vivo." (PMID 39343985, 2025). "In CRC, the NOTCH1-mediated glycosylation-dependent Notch signaling pathway augments the stem-like characteristics of tumor cells, with NOTCH1 expression facilitating enhanced proliferation, migration, and invasion." (PMID 40842994, 2025). "As tumor cells migrate deeper into the dermis, they acquire additional alterations, including mutations in genes such as PTEN, NOTCH1, and CDKN2A, that contribute to proliferative advantage, immune evasion, and matrix degradation." (PMID 41463022, 2025). "Our clinical analysis also uncovered a distinct relationship among NOTCH1, tumor heterogeneity, and ICB survival in SCLC." (PMID 40627448, 2025). "Research has revealed that NOTCH1 has a tumor-suppressive role in LUSC models but promotes tumor growth in LUAD." (PMID 40083325, 2025). "Multiplexed immunofluorescence staining analysis of tumor sections revealed that NOTCH1-knockout tumors had significantly reduced microvascular density compared with NOTCH1-non-knockout tumors." (PMID 40691441, 2025). "Inactivating NOTCH1 mutations have been frequently observed in human SCLC tissue samples, and previous studies have highlighted the tumour-suppressive roles of NOTCH1 by cell culture and mouse models." (PMID 40595415, 2025). "Notch1 expression was observed in both tumor and stromal cells in most samples, corroborating reports in the literature documenting Notch1 expression in various cancers and its role in tumorigenesis." (PMID 40060224, 2025). "For example, miR-34a directly targets Notch1, inhibiting tumor cell proliferation, migration, and invasion." (PMID 40621472, 2025). "Reverse transcription quantitative polymerase chain reaction (RT-qPCR) results demonstrated that NOTCH1 mRNA showed higher levels in tumor tissues from both OSCC and MEC patients when compared to healthy tissues (p<0.05)." (PMID 40672020, 2025). "The key roles of NOTCH1 in the tumor cells are angiogenesis, differentiation, proliferation, and migration." (PMID 41451346, 2025). "Therapeutic Strategies: Preclinical studies demonstrate that selective anti-Notch1 monoclonal antibodies (e.g., Omp-18) can significantly attenuate tumor cell proliferative capacity and metastatic dissemination through ligand-binding domain blockade." (PMID 40621472, 2025).
tumor (continued). "In conclusion our study provides the first evidence of the tumor suppressor role of Bcor coupled with Notch1 deregulation in a pre-clinical model of high-grade lymphoid malignancy mimicking human RT." (PMID 40113912, 2025). "Using spatially resolved multi-omic profiling of clinical NPC samples and experimental validation, a tumor-endothelial crosstalk mechanism is identified, driven by the NOTCH1-FTO-SPARC axis." (PMID 41311280, 2025). "According to the studies, increased levels of NOTCH1 in the tumour environment alter how immune suppression occurs." (PMID 40672020, 2025). "In PC and TNBC, NOTCH1 inhibition combined with anti-PD-1 therapy reduces tumor growth and activates anti-tumor immunity." (PMID 41417432, 2025). "While KLF9 acts as a tumor suppressor in metastatic niches by suppressing cancer stemness and Notch1/Slug-driven aggressiveness, its paradoxical upregulation in primary tumors suggests a microenvironment-specific duality." (PMID 40860800, 2025). "Later, Maraver and colleagues confirmed the tumour suppressive role of NOTCH1, but they observed another role for NOTCH2, whereas NOTCH3 was not studied." (PMID 41008920, 2025). "IHC results demonstrated that CRTC1 knockdown amplified the reduction in PD-L1 expression induced by atezolizumab, whereas Notch1 overexpression elevated PD-L1 expression in tumor tissues." (PMID 40977688, 2025). "Delta-like ligand 3 (DLL3) functions as an inhibitory ligand of the Notch pathway by interacting with Notch receptors (Notch1-4), promoting malignant tumor transformation." (PMID 41375037, 2025). "In a multivariate analysis with regard to RFI, including nodal status and biological tumour types, we observed a hazard ratio of 2.1 (95% CI 1.08–4.12,) for patients with NOTCH1 mRNA overexpressed tumours." (PMID 39153127, 2025). "In Neuroendocrine Tumors (NETs), Notch expression is reduced, with concomitant mutations in Notch pathway components; scientific evidence shows that Notch1 activation inhibits cell proliferation, indicating a tumor suppressive role." (PMID 41294868, 2025). "CosMx spatial transcriptomics platform uncovered the expression of NOTCH1-3 in ~40% of tumor cells in 1 human CPC sample." (PMID 40128799, 2025). "Reducing Musashi-1 levels decreases Notch-1 signaling, leading to increased apoptosis and suppressed tumor growth, possibly due to the role of Musashi-1 in maintaining stem-like properties in cancer." (PMID 40003637, 2025). "Most of these specific mutations (n = 20; 80%) were exclusive to NAT, including those affecting key genes such as NOTCH1 (the most mutated gene), FAT1, or PPARD; while 20% were shared between NAT and tumor tissue, affecting genes such as CDKN2A." (PMID 40465458, 2025). "For example, activation of Notch1 can inhibit apoptosis by upregulating anti-apoptotic proteins (such as Bcl-2 and Survivin), thereby increasing tumor cell survival." (PMID 40621472, 2025). "Mechanistically, CRTC1 interacted with Notch1 to activate the Notch1/Akt pathway, stimulating PD-L1 upregulation, thereby facilitating tumor immunosuppression and growth." (PMID 40977688, 2025). "In a recent study, CSF2 was shown to trigger ubiquitination and subsequent downregulation of Notch1 in MSCs, thus fostering the tumor phenotype and functionality." (PMID 41312360, 2025). "This suggests that Notch‐1 activation promoted orthotopic tumour growth while inhibiting metastatic progression." (PMID 39343985, 2025). "In Notch1 knockdown, PD‐L1 expression on the tumor cell surface increased, while cytoplasmic PD‐L1 expression decreased." (PMID 41026775, 2025). "Female nude mice were employed to investigate the effects of varying degrees of Notch‐1 activation on the migration of tumour collective cells." (PMID 39343985, 2025).
tumor (continued). "Its mechanism of action involves cooperation with NOTCH1, which can act both as an oncogene and tumor suppressor." (PMID 40004558, 2025). "Employing Dox-inducible POSTN knockdown in SCLC and NOTCH1 functional inhibitor DAPT in fibroblasts effectively improved the anti-tumor efficacy, offering a novel therapeutic strategy to impede SCLC liver metastasis." (PMID 39762921, 2025). "Several studies have discovered that NOTCH1 overexpression decreases the efficiency of the immune system within the tumour environment." (PMID 40672020, 2025). "Ultimately, their findings supported a tumour-suppressive function for NOTCH1, and they proposed a similar suppressive role for NOTCH2 and NOTCH3." (PMID 41008920, 2025). "Patients who received adjuvant chemotherapy and had high NOTCH1 mRNA expression in the tumour (n = 86) were three times more likely to have an RFI event (adjusted hazard ratio 3.1, 95% CI 1.321–7.245, p = 0.009)." (PMID 39153127, 2025). "According to these data, the role of NOTCH in cancer remains controversial, and there is growing evidence for the dual function of NOTCH1 as both a tumor suppressor or an oncogene depending on the cellular and tissue context." (PMID 41009728, 2025). "In vitro data revealed that CRTC1 in NSCLC cells upregulates PD-L1 by directly targeting the Notch1/Akt signaling pathway, thereby suppressing T-cell survival and cytotoxic activity, ultimately triggering tumor reprogramming in NSCLC cells." (PMID 40977688, 2025). "This study aimed to evaluate the expression of Notch1 and CD10, both of which have been implicated in tumor progression and therapy resistance." (PMID 40060224, 2025). "In fact, the tumor and normal cells have exhibited distinct molecular behavior in different MFDs regarding NOTCH 1 and hsa_circ_0005986 levels." (PMID 40761890, 2025). "Preclinical studies have shown that low, non-cytotoxic doses of DAC induce targeted demethylation and upregulate tumour-suppressive genes such as NOTCH1, thereby restoring transcriptional activity and impairing tumour progression." (PMID 40806634, 2025). "Another example is Bacteroides fragilis, a gut bacterium also found in the mammary gland, whose toxin can promote epithelial hyperplasia, tumor growth, and metastasis via the β-catenin–Notch1 axis." (PMID 40599853, 2025). "Through the identification of this pattern, overexpression of NOTCH1 was shown to contribute to cancer immune evasion and tumour aggressiveness." (PMID 40672020, 2025). "Growth signaling aberrations, epigenetic dysregulation, and disruption of cell fate determination define the somatic mutational profile of our patient's tumor, which includes mutations in PIK3R1, KMT2D, and NOTCH1." (PMID 40124187, 2025). "Whole genome sequencing of the patient’s tumour identified various mutations including AKT1 and NOTCH1, as well as the TP63-TBL1XR1 gene fusion." (PMID 40715645, 2025). "IL‐10, secreted by tumor‐associated macrophages, stimulates cancer stem cell‐like characteristics in NSCLC cells via the JAK1/STAT1/NF‐κB/Notch1 pathway." (PMID 41223031, 2025). "miR-34a functions as a tumor suppressor by regulating genes involved in apoptosis, such as Notch1, leading to increased apoptosis in breast cancer cells." (PMID 40958878, 2025). "The results showed that compared with the control group, the tumor volume and growth rate in the radiotherapy-only group (Rad) were significantly reduced, while those in the NOTCH1 overexpression group (oe-NOTCH1) were significantly increased." (PMID 41306984, 2025). "For example, miR-34a acts as a tumor-suppressive miRNA by inhibiting Notch1 expression, thus suppressing tumor cell proliferation and metastasis." (PMID 40621472, 2025).
tumor (continued). "In brief, we uncovered an unanticipated ablation of the Notch1‐p15‐mediated tumor suppression by ANXA1 in AML through the ubiquitination‐proteasome degradation of NICD to block the transcriptional activation of p15 in vitro and in vivo." (PMID 39447086, 2024). "We also demonstrated that Crenigacestat inhibits iCCA tumor progression in NOTCH1/HES1/THY1-positive xenograft models." (PMID 39415286, 2024). "We and others have previously shown that Notch1 inhibition delays tumor growth and promotes cell death." (PMID 39491031, 2024). "Nonetheless, we have previously shown that a critical feature of metastasis in the Notch1-driven KPN tumours is TGFβ pathway-mediated neutrophil infiltration." (PMID 38168062, 2024). "Previous studies showed that Notch1 can promote invasion and metastasis in many tumor cells, including GC cells." (PMID 39172098, 2024). "NOTCH1 signalling in CAFs serves as a molecular switch, which modulates tumour heterogeneity and aggressiveness by regulation of the plasticity and stemness of CSCs in melanoma." (PMID 38926351, 2024). "In the same context, Treating mice bearing SEC with free P. crinita extract (25, 50 mg/kg) revealed a sustainable decrease in Notch 1 protein values (18.4% and 51.6%, respectively), following the tumor control group." (PMID 38469406, 2024). "Tumor cells activate Notch1 signaling activity in tumor endothelial cells facilitating tumor cell transmigration, intravasation, and metastasis." (PMID 39325128, 2024). "Tumour specific variants in CDKN2A, NOTCH1 and KMT2D present at baseline were detected longitudinally in ctDNA and increased in frequency at recurrence." (PMID 38846976, 2024). "In our study, this type of tumor stained differently than adenocarcinomas for CK18 and exhibited mutations for Notch 1 and APC." (PMID 39123450, 2024). "Pretreatment tumor biopsies revealed low Notch1 levels and a 10-fold increase in Notch1 activity on a post-VPA treatment tumor biopsy." (PMID 38279330, 2024). "Notch1 is involved in cell fate determination in the development and maintenance of tissue homeostasis and is an important regulator of tumor angiogenesis." (PMID 38650654, 2024). "Overall, our data suggest that CAD204520 inhibits NOTCH1 PEST mutations in both cell lines and in primary CLL samples, retaining the advantageous anti-tumor effect on mutated WT cells." (PMID 38255842, 2024). "Studies have reported that Notch1 expression can be induced by high-dose IR, while inhibiting Notch1 can enhance the radiosensitivity of tumor cells." (PMID 39273235, 2024). "Intrathecal administration of a NOTCH1-blocking antibody to MB tumor-bearing mice results in a lower incidence of spinal metastasis compared to the control group." (PMID 38674001, 2024). "Our BioID study attempted to mimic those conditions in tumor cells to capture previously unidentified proximal interacting proteins of Notch1." (PMID 38043798, 2024). "NOTCH1 mutations were described for the first time in HNSCC and revealed a tumor suppressive behavior of NOTCH1 in HNSCC, which contrasts with the common oncogenic effect of NOTCH1 mutations in hematolymphoid malignancies." (PMID 39613893, 2024). "miR-34a negatively regulates Notch1 expression, thus becoming a regulatory factor involved in tumor invasion and metastasis." (PMID 38813102, 2024). "Although both Notch1 and Notch4 are highly expressed on tumor ECs, only the effects of Notch1 signal inhibition have been intensively studied." (PMID 38984877, 2024). "Concurrently, Notch1 signaling was activated in GSC; Notch1 signaling and expression of stemness-associated proteins were increased in normal GBM cells treated with GSC exosomes and in the resulting tumor tissues." (PMID 38672496, 2024). "The activation of Notch 1 inhibits tumor growth, suggesting that Notch 1 serves as a tumor suppressor." (PMID 38279330, 2024).